IQGAP1 (IQ motif containing GTPase activating protein 1)
Diseases named in the same sentence as IQGAP1 in open-access papers (continued):
Sharing a sentence is not in itself a finding about the gene and the disease.
gastric cancer (19 papers, 2004 to 2025). A primary or metastatic malignant neoplasm involving the stomach. "Membrane-localized IQGAP1 is associated with higher grades of gastric cancer, possibly due to reduced cell–cell adhesion." (PMID 34439095, 2021). "However, another study suggested the opposite, that mice deficient in IQGAP1 showed a higher incidence of gastric cancer after infection with Helicobacter pylori (H. pylori)." (PMID 41188920, 2025). "We also discovered that IQGAP1 is involved in trastuzumab resistance in gastric cancer cell lines and identified 2 new mutations of the HER2 gene that may be correlated with acquired resistance to the drug." (PMID 26919099, 2016). "During gastric cancer progression, IQGAP1 directly interacts with RhoC, enhancing the expression of cyclins E and D1, indirectly affecting the G1/S transition and promoting cell proliferation." (PMID 41035668, 2025). "Recent research indicates that menin inhibits gastric cancer cell proliferation by suppressing IQGAP1 and downregulating PI3K and NF-κB expression." (PMID 41035668, 2025). "Further elucidating the mechanisms of IQGAP1 in gastric cancer progression and incorporating these findings into targeted therapies to enable early detection and improved prognosis for gastric cancer patients will remain a critical area of research." (PMID 41035668, 2025). "Research indicates that various biomolecules interact with IQGAP1, enhancing the metastasis and invasion of gastric cancer cells." (PMID 41035668, 2025). "Recent studies have discovered other molecular partners involved in IQGAP1-mediated migration and invasion of gastric cancer cells." (PMID 41035668, 2025). "The mechanisms by which IQGAP1 participates in the progression of gastric cancer are complex and not fully understood." (PMID 41035668, 2025). "IQGAP1 also acts as a scaffold protein regulating alternative splicing (AS) of different gene subgroups in gastric cancer cells." (PMID 41035668, 2025). "PGC can downregulate its interacting protein IQGAP1 and inhibit the Rho-GTPase pathway, thereby participating in the inhibition of gastric cancer cell migration and invasion." (PMID 38791874, 2024). "Together, IQGAP1 and the heterogeneous nuclear ribonucleoprotein M (hnRNPM) have been shown to stimulate gastric cancer cell growth, while their genetic depletion prompts cell cycle arrest that subsequently causes tumor progression." (PMID 36276098, 2022). "Many studies have explored the Wnt/E-cadherin/β-catenin pathway downstream of IQGAP1 as a potential target for gastric cancer 63-65, and it has been reported that IQGAP1 gene knockout leads to gastric dysplasia in mice." (PMID 35154449, 2022). "Increased levels of IQGAP1 were observed in gastric cancer cell lines with acquired trastuzumab resistance." (PMID 34439095, 2021). "On the other hand, some evidence indicates that IQGAP1 can act as a tumor suppressor in gastric cancer." (PMID 34439095, 2021). "RhoC, a Rho GTPase overexpressed in gastric cancer, binds to IQGAP1 and regulates cell proliferation and cell migration in an IQGAP1-dependent manner." (PMID 34439095, 2021). "The IQGAP1 gene is amplified in gastric cancer cell lines, and levels of IQGAP1 protein are increased in gastric cancers." (PMID 34439095, 2021). "The same group further showed that the IQGAP1-RhoC complex significantly stimulated the proliferation of gastric cancer cells." (PMID 32824461, 2020). "In the present work we showed that IQGAP1 knockdown in gastric cancer leads to the abrogation of trastuzumab resistance and to restored drug sensitivity." (PMID 26919099, 2016). "In conclusion, our study revealed that high IQGAP1 expression leads to resistance to trastuzumab in gastric cancer." (PMID 26919099, 2016). "Our previous results have documented that the expression of IQGAP1 and RhoC were increased in gastric cancer tissues and cancer cell lines." (PMID 23145020, 2012).
gastric cancer (continued). "Our previous study showed that the higher expressions of RhoC and IQGAP1 in gastric cancer tissue were significantly reversely correlated with the differentiation of the gastric cancer cells." (PMID 23145020, 2012). "In conclusion, our results suggest that RhoC stimulates the proliferation of gastric cancer cells through recruiting IQGAP1 as an effector." (PMID 23145020, 2012). "In this study, the expression level of IQGAP1 and RhoC and their biological activities in gastric cancer cell line BGC-823 were adjusted through infection with adenoviral constructs or transfection with plasmid DNA or siRNA." (PMID 23145020, 2012). "The results showed that RhoC, IQGAP1 and the C-terminal fragment of IQGAP1 significantly stimulated the proliferation of gastric cancer cells, and enhanced the expression of cyclin E and cyclin D1." (PMID 23145020, 2012). "Herein we reported the proliferation stimulating effect of RhoC and IQGAP1 on gastric cancer cells and the interaction between two proteins in regulating the proliferation of gastric cancer cells." (PMID 23145020, 2012). "However, the function of IQ motif-containing GTPase-activating protein 1 (IQGAP1) in gastric cancer is controversial." (PMID 41188920, 2025). "Rho/Rho-associated protein kinase (ROCK) pathway also plays a key role in gastric cancer cell metastasis and invasion by recruiting IQ domain GTPase activating protein 1 (IQGAP1) 13-16, while IL-6 induces gastric cancer cell invasion by activating the c-Src/RhoA/ROCK signaling pathway." (PMID 40092690, 2025). "Nevertheless, the reduction of IQGAP1 has been associated to an inhibition of EMT in gastric cancer, and the clear role of IQGAP1 in EndMT has not been clearly established yet." (PMID 34458332, 2021). "In another study focusing on Helicobacter(H.)pylori infection, which can cause gastric cancer, mice lacking IQGAP1 tend to develop a higher incidence of gastrointestinal neoplasia upon infection with H. pylori." (PMID 34439095, 2021). "IQGAP1 is frequently up-regulated in a subset of gastric, colon, and ovarian cancers and is localized on chromosome band 15q26, a region that shows amplification in gastric cancer." (PMID 32824461, 2020). "From the literature, RhoC was proposed to regulate proliferation through interaction with IQGAP1 in gastric cancer, suggesting that RhoC and IQGAP1 could stimulate the proliferation of gastric cancer." (PMID 32824461, 2020). "Moreover, IQGAP1 protein is overexpressed in squamous cell and hepatocellular carcinoma, astrocytoma, and aggressive forms of gastric cancer." (PMID 26919099, 2016). "The abnormal expression of IQGAP1 is related to poor prognosis in gastric cancers." (PMID 25398317, 2014). "To primarily explore the downstream mechanism through which RhoC/IQGAP1 regulate the proliferation of gastric cancer cells, we investigated the effect of RhoC/IQGAP1 on the expression of cell cycle related proteins, including cyclin E, cyclin D1, cyclin B and cyclin dependent kinase (CDK)." (PMID 23145020, 2012). "Interestingly, IQGAP1 has been previously suggested to play a tumor-promoting role in multiple cancers, including gastric cancer, suggesting that menin may also help suppress gastric cell proliferation through the repression of IQGAP1." (PMID 39336822, 2024). "In addition, two gastric cancer cell lines with IQGAP1 overexpression had amplification of IQGAP1." (PMID 32824461, 2020). "Another study suggested that integrin-like kinase (ILK) activates NF-κB through IQGAP1-mediated RAS-MAPK signaling and regulates cell migration and proliferation in gastric cancer cells." (PMID 34439095, 2021). "ILK facilitates the formation of the IQ motif-containing GTPase-activating protein 1 (IQGAP1)-Ras complex leading to activation of Ras/c-Raf/MEK1/2/ERK1/2, ribosomal S6 kinase and NF-κB signaling in AGS, SNU-1, MKN45, GES-1 gastric cancer cell lines." (PMID 28350359, 2017).
gastric cancer (continued). "One study found an interaction between pepsinogen (PGC) and IQGAP1, with a significant negative correlation between their expressions in gastric cancer cells." (PMID 41035668, 2025). "The study also found that ASAP1, through IQGAP1-activated CDC42, may upregulate EGFR-MAPK signaling, contributing to resistance to common gastric cancer chemotherapy drugs such as 5-fluorouracil and oxaliplatin." (PMID 41035668, 2025). "Regarding IQGAP1 sustaining Ras activity in gastric cancer cells, IQGAP1 but not IQGAP3 mediated cell growth through an ERK1/2-regulated NF-κB activation pathway." (PMID 25398317, 2014). "Our previous research results showed that both Ras homolog family member C (RhoC) and IQ-domain GTPase-activating protein 1 (IQGAP1) were over-expressed in gastric cancer tissues and cells, but their role in tumorigenensis has not been addressed clearly." (PMID 23145020, 2012). "Interestingly, knockdown of IQGAP1 alone, but not RhoC, attenuated migration and proliferation of gastric cancer cells, indicating the crucial role of IQGAP1 in gastric cancer tumorigenesis." (PMID 32824461, 2020). "Based on the finding that PI3K/PTEN/HSP90-regulated ILK upregulation induces non-canonical IQGAP1/Ras/ERK1/2-mediated NF-κB activation and growth advantages in gastric cancer cells, targeting this pathway may be beneficial when used in combination with other anticancer agents." (PMID 25398317, 2014).
glioma (17 papers, 2008 to 2025). A benign or malignant brain and spinal cord tumor that arises from glial cells (astrocytes, oligodendrocytes, ependymal cells). "In vivo experiments have validated the role of IQGAP1, demonstrating that knocking down IQGAP1 expression arrests the proliferation of low-grade glioma cells, with most cells halting in the G0/G1 phase." (PMID 41035668, 2025). "Immunohistochemistry analysis demonstrated that the protein expression level of IQGAP1 in GBMLGG were higher than those in the adjacent tissues, which indicated the oncogenic roles of IQGAP1 in glioma." (PMID 38546389, 2024). "This study first validated the oncogenic roles of IQGAP1 in glioma using Immunohistochemistry analysis, which showed that the protein expression level of IQGAP1 in GBMLGG were higher than those in the normal adjacent tissues." (PMID 38546389, 2024). "IQGAP1 is characteristically over-expressed in various types of cancers including hepatocellular, prostate, glioma, head-and-neck and breast." (PMID 39357822, 2024). "Using the experimental glioma xenograft model, we discovered that IQGAP1 aided in the in vivo expansion of the GBMLGG tumor." (PMID 38546389, 2024). "Mechanistically, TRIM56 was found to interact with IQGAP1 to promote its K63-linked ubiquitination and inhibit degradative K48-linked ubiquitination at Lys-1230, thus promoting CDC42 activation in glioma cells." (PMID 36870986, 2023). "Knockdown of IQGAP1 inhibits both Rac1- and Cdc42-mediated migration and invasion of glioma cells and leads to the suppression of several other components of the invasion process such as MMPs." (PMID 32089990, 2020). "It is therefore not surprising that in addition to Cdc42, high levels of proteins that interact with Cdc42 like IQGAP1 are correlated with poor survival of patients with glioma." (PMID 32089990, 2020). "MiR-124-3p restoration represses the migration and/or invasion of glioma cells by targeting Capn4, IQGAP1, iASPP, and PIM1." (PMID 31708690, 2019). "Recent studies have reported that IQGAP1 is accumulated in the plasma membrane at the invasive front in several cancer types, including gliomas." (PMID 28098764, 2017). "The origin of glioma-infiltrating myeloid cells (GIMs) surrounding IQGAP1+ clusters seem to be from resident brain macrophages (microglia), since cells were Iba1+/CD31−." (PMID 28098764, 2017). "Knockdown of IQGAP1 in inducible U251MG glioma cells was performed to elucidate the functional role of IQGAP1." (PMID 27486972, 2016). "Studies have reported inhibition of Rac1 activity following overexpression of an IQGAP1 construct lacking a Rac1 binding site in HEK 293T cells and following RNAi-mediated silencing of IQGAP1 in U87MG glioma cells upon serum stimulation." (PMID 24355937, 2013). "In conclusion, our study provides insights into the mechanisms through which TRIM56 promotes glioma motility, i.e., by regulating IQGAP1 ubiquitination to promote CDC42 activation, which might be clinically targeted for the treatment of glioma." (PMID 36870986, 2023). "Our results demonstrated that only CA-Cdc42 recruits and binds to IQGAP1, and this interaction can promote actin cytoskeletal rearrangement that may lead to increased invasion and migration of glioma cells." (PMID 27486972, 2016). "We found that TRIM56 expression was directly regulated by SP1, and TRIM56 enhanced glioma cell migration and invasion via activation of CDC42, which was mediated through the interaction of TRIM56 with IQGAP1 to increase the K48-K63-linked ubiquitination transition of IQGAP1." (PMID 36870986, 2023). "Moreover, restoration of miR-124a could inhibit glioma cell proliferation and invasion through miR-124a blocking the expression of the IQGAP1 gene and downstream β-catenin and cyclin D1 and PIM1 in astrocytoma cancer cells." (PMID 29138748, 2017).
glioma (continued). "Our study identified TRIM56 as a glioma-favoring factor that promotes the motility of glioma cells in vitro and in vivo by potentiating CDC42 activation in an IQGAP1-dependent manner." (PMID 36870986, 2023). "IHC and Western blot analyses of clinical glioma tissue samples revealed a strong positive correlation between TRIM56 and IQGAP1 expression at the protein level." (PMID 36870986, 2023). "In this study, we show evidence of IQGAP1 involvement in GBM onco-biology, including glioma-infiltrating myeloid cells (GIMs), remaining neurons, endothelial vascular cells, and astrocytes." (PMID 28098764, 2017). "Despite of the different molecular pathogenesis and progression of gliomas giving rise to primary or secondary GBM, within the limits of our study we have not seen differences in the scattered cellular expression of IQGAP1 between them." (PMID 28098764, 2017). "In addition, Arf6 is also found to form complexes with Rac1 and IQGAP1 in glioma cells upon HGF stimulation, and IQGAP1 is essential for Arf6-induced Rac1 activation and cell migration." (PMID 22701712, 2012).
liver cancer (14 papers, 2010 to 2025). An epithelial or non-epithelial malignant neoplasm that arises from the liver. "The loss of IQGAP2 in mice spontaneously leads to liver cancer development, which is also IQGAP1-dependent." (PMID 34439095, 2021). "Among the different types of protein, IQGAP1 has been linked to the progression of several cancers including liver cancer (Johnson & Sharma, 2009; Sanchez-Laorden, Viros & Marais, 2013)." (PMID 33062407, 2020). "Furthermore, the associations of IQGAP1 and β-catenin expression were confirmed to play important roles in liver cancer progress from clinic immunohistochemistry analysis for liver cancer tissues as follows." (PMID 26252773, 2015). "Hence, it is tempting to speculate that the induction of liver cancer caused by cholestasis may require the loss of IQGAP1-Hippo pathway signalling and the activation of proliferative signals mediated by other pathways." (PMID 33672268, 2021). "In HBV-positive liver cancer cells, IQGAP1 is significantly upregulated compared to HBV-negative cells." (PMID 41035668, 2025). "Our results also showed that disruption of IQGAP1/FOXM1 resulted in the reduction of CD133+ population that contribute to the stemness of liver cancer cells." (PMID 37202772, 2023). "IQGAP1 is a scaffold protein which facilitates the interaction of mTOR and Akt and thus promotes liver cancer progression." (PMID 37202772, 2023). "Engineered HLC9-EVs encapsulated sgIF, contributed to the suppression of IQGAP1/FOXM1and subsequent significant reduction of CD133+ liver cancer stem cells." (PMID 37202772, 2023). "In the diethylnitrosamine (DEN)-induced mouse liver cancer model, mRNA expressions of IQGAP1 and the Ras gene family were highly elevated in HCC cells compared to normal hepatocytes, and their expression increased in response to the dosage of DEN." (PMID 35785216, 2022). "Our results revealed that the treated group with IQGAP1-shRNA with DENA developed very few cases of hepatic cancer when compared with the positive control group." (PMID 36276098, 2022). "Researchers have suggested that IQGAP1 is oncogenic, and its upregulation leads to the induction of liver cancer, while IQGAP2 acts as a suppressor gene." (PMID 36276098, 2022). "Discover a new tool for the prevention of hepatic cancer in vivo through the silencing of IQGAP1 mRNA and the evaluation of its effects on serious inflammatory as well as pre- and antiapoptotic signaling parameters was our aim of this study." (PMID 36276098, 2022). "Through modulation of these genes, the silencing of IQGAP1 can improve liver function and act as an antioxidant and anti-inflammatory event and, consequently, prevent the induction of hepatic cancer by outer effectors (e.g., chemicals, radiation, etc.)." (PMID 36276098, 2022). "IQGAP1 is oncogenic and its up-regulation leads to the induction of liver cancer so the inhibition or knockdown of the expression of IQGAP1 is a significant reason for prevention of the initiation and development of hepatic cancer." (PMID 36276098, 2022). "This study aimed to uncover new avenues for the treatment of hepatic cancer in vivo through the silencing of IQGAP1 and the assessment of its effects on critical inflammatory as well as pre- and antiapoptotic signaling parameters." (PMID 36276098, 2022). "In the current study, we found that IQGAP1-shRNA can markedly attenuate the DENA-induced liver cancer development through modulation of TRAIL, IL-8 receptors, and other apoptotic factors." (PMID 36276098, 2022). "IQGAP1 is an inducer gene for cancer, and it has been reported to induce liver cancer in both humans and animals." (PMID 36276098, 2022). "In our study, we found that the knockdown of IQGAP1 induces the production of pro-inflammatory cytokines that were otherwise suppressed by the DENA-induced liver cancer, through the activation of TNF-α and interleukins." (PMID 36276098, 2022).